KCNC4 (potassium voltage-gated channel subfamily C member 4)
Description:
Voltage-gated potassium channel that opens in response to the voltage difference across the membrane, forming a potassium-selective channel through which potassium ions pass in accordance with their electrochemical gradient. The channel displays rapid activation and inactivation kinetics.
Synonyms: C1orf30; Kv3.4; HKSHIIIC; KSHIIIC
Tractability: Small molecule: an approved drug acts on it; it belongs to a druggable protein family. Antibody: its Gene Ontology location is reachable by antibodies, with high confidence; UniProt predicts a signal peptide or a membrane-spanning region.
Gene: Protein-coding gene on chromosome 1 (110,210,314 to 110,283,100, forward strand). Ensembl gene ENSG00000116396.
Subcellular location: Membrane
Subcellular location (Human Protein Atlas): Cytosol; Nucleoli
Pathways (Reactome):
Neuronal System: Voltage gated Potassium channels
Gene Ontology:
Molecular function: protein binding; voltage-gated potassium channel activity; delayed rectifier potassium channel activity; potassium channel activity; gated channel activity; monoatomic ion channel activity
Biological process: action potential; chemical synaptic transmission; potassium ion transmembrane transport; potassium ion transport; monoatomic ion transport; protein homooligomerization; transmembrane transport
Cellular component: axon terminus; dendrite membrane; neuronal cell body membrane; plasma membrane; postsynaptic membrane; presynaptic membrane; voltage-gated potassium channel complex; membrane
Genetic constraint (gnomAD): Loss-of-function variants: 23 observed, 40.54 expected, observed/expected ratio (o/e) 0.57, 90% interval 0.41 to 0.8. The upper end of that interval is the gene's LOEUF score, 0.8, which puts it in group 3 of 6, group 1 being the genes least tolerant of losing a copy. Missense variants: 751 observed, 919.88 expected, observed/expected ratio (o/e) 0.82, 90% interval 0.77 to 0.87. Synonymous variants: 422 observed, 407.55 expected, observed/expected ratio (o/e) 1.04, 90% interval 0.95 to 1.12.
Homologues: Orthologues: chimpanzee KCNC4 (97% identical), macaque KCNC4 (96% identical), rat Kcnc4 (95% identical), mouse Kcnc4 (95% identical), pig KCNC4 (94% identical), dog KCNC4 (92% identical), guinea pig KCNC4 (89% identical), tropical clawed frog kcnc4 (73% identical), rabbit KCNC4 (59% identical). Paralogues in human: KCNC2 (66% identical), KCNC3 (66% identical), KCNC1 (64% identical), KCNA4 (30% identical), KCNB2 (30% identical), KCNA3 (30% identical), KCNA1 (30% identical), KCNA5 (29% identical), KCNA2 (29% identical), KCNA6 (28% identical), KCNA7 (28% identical), and 19 more.
Diseases named in the same sentence as KCNC4 in open-access papers:
KCNC4 is named in the same sentence as 35 diseases in open-access papers, as found by Europe PMC text mining. Sharing a sentence is not in itself a finding about the gene and the disease. The quoted sentences say what the papers report.
angiosarcoma (1 paper, 2016). A malignant tumor arising from the endothelial cells of the blood vessels. "Notably, expression of several potassium channels is modified in bladder cancer vessels vs controls (KCNC4, KCNG4, KCNS2) and in angiosarcoma vs controls (namely KCNJ16, KCNQ2, KCNJ15, KCNJ12, KCNJ1)." (PMID 27716384, 2016).
cardiac arrhythmia (1 paper, 2023). Any disturbances of the normal rhythmic beating of the heart or MYOCARDIAL CONTRACTION. "In addition, AGTR1 and NT5C2 were associated with pre-hypertension (FDR = 3.53E−02), and AGTR1 and KCNC4 were associated with adverse events associated with cardiac arrhythmia (FDR = 3.59E−02)." (PMID 37210443, 2023).
head and neck cancer (1 paper, 2023). A primary or metastatic malignant neoplasm affecting the head and neck. "Similarly, in head and neck cancer, a high expression of KCNC4 is associated with laryngeal and pharyngeal squamous cell carcinoma; in accordance, the silencing of KCNC4 by siRNA inhibits cell proliferation in the G2/M phase." (PMID 37408210, 2023).
cancer (8 papers, 2017 to 2025). A tumor composed of atypical neoplastic, often pleomorphic cells that invade other tissues. "In CC HPV+ cell lines, the potassium voltage-gated channel subfamily C member 4 (KCNC4 or Kv3.4) and the AKT pathway have been shown to regulate vimentin expression, and the use of blood depressing substance II (BDS-II) as a channel blocker decreases vimentin expression and cancer cell migration." (PMID 37408210, 2023).
KCNC4 also shares sentences with these, for which no sentence is quoted: Alzheimer disease (4 papers); tumor (4); epilepsy (2); head and neck squamous cell carcinoma (2); Parkinson’s (2); spinal cord injury (2); adenocarcinoma (1); amyloid (1); autism (1); bladder cancer (1); breast carcinoma (1); cardiovascular diseases (1); colon cancer (1); endotoxemia (1); glioblastoma (1); Huntington disease (1); Hypertension (1); laryngeal carcinoma (1); lung adenocarcinoma (1); lung carcinoma (1); neurodegenerative disease (1); neurological disorders (1); neuropathic pain (1); oral squamous cell carcinoma (1); Pain (1); periodic paralysis (1); pharyngeal squamous cell carcinoma (1); spinocerebellar ataxia type 13 (1); squamous cell carcinoma (1); substance dependence (1).
A further 1 disease shares a sentence with KCNC4 in 1 paper.